PLA2G10 (phospholipase A2 group X)
Description:
Secretory calcium-dependent phospholipase A2 that primarily targets extracellular phospholipids. Hydrolyzes the ester bond of the fatty acyl group attached at sn-2 position of phospholipids with preference for phosphatidylcholines and phosphatidylglycerols over phosphatidylethanolamines. Preferentially releases sn-2 omega-6 and omega-3 polyunsaturated fatty acyl (PUFA) chains over saturated fatty acyls. Contributes to phospholipid remodeling of very low-density lipoprotein (VLDL), low-density lipoprotein (LDL) and high-density lipoprotein (HDL) particles. Hydrolyzes LDL phospholipids releasing unsaturated fatty acids that regulate macrophage differentiation toward foam cells. Efficiently hydrolyzes and inactivates platelet activating factor (PAF), a potent lipid mediator present in oxidized LDL. May act in an autocrine and paracrine manner. Secreted by lung epithelium, targets membrane phospholipids of infiltrating eosinophils, releasing arachidonate and boosting eicosanoid and cysteinyl leukotriene synthesis involved in airway inflammatory response (By similarity). Secreted by gut epithelium, hydrolyzes dietary and biliary phosphatidylcholines in the gastrointestinal lumen (By similarity). Plays a stem cell regulator role in colon epithelium. Within intracellular compartment, mediates Paneth-like cell differentiation and its stem cell supporting functions by inhibiting the Wnt signaling pathway in intestinal stem cell (ISC). Secreted in the intestinal lumen upon inflammation, acts in an autocrine way and promotes prostaglandin E2 synthesis that stimulates Wnt signaling pathway in ISCs and tissue regeneration (By similarity). May participate in hair follicle morphogenesis by regulating phosphatidylethanolamines metabolism at the outermost epithelial layer and facilitating melanin synthesis (By similarity). By releasing lysophosphatidylcholines (LPCs) at sperm acrosome, controls sperm cell capacitation, acrosome reaction and overall fertility (By similarity). May promote neurite outgrowth in neuron fibers involved in nociception (By similarity). Contributes to lipid remodeling of cellular membranes and generation of lipid mediators involved in pathogen clearance. Cleaves sn-2 fatty acyl chains of phosphatidylglycerols and phosphatidylethanolamines, which are major components of membrane phospholipids in bacteria. Displays bactericidal activity against Gram-positive bacteria by directly hydrolyzing phospholipids of the bacterial membrane. In pulmonary epithelium, may contribute to host defense response against adenoviral infection. Prevents adenovirus entry into host cells by hydrolyzing host cell plasma membrane, releasing C16:0 LPCs that inhibit virus-mediated membrane fusion and viral infection. Likely prevents adenoviral entry into the endosomes of host cells. May play a role in maturation and activation of innate immune cells including macrophages, group 2 innate lymphoid cells and mast cells (By similarity).
Synonyms: sPLA2-X; GXPLA2; GXSPLA2; SPLA2
Tractability: Small molecule: a drug acting on it is in phase 2 or 3 trials; a structure with a bound ligand is known; a high-quality ligand is known; it has a binding pocket of medium quality; it belongs to a druggable protein family. Antibody: UniProt places it where antibodies can reach, with high confidence; its Gene Ontology location is reachable by antibodies, with high confidence; UniProt predicts a signal peptide or a membrane-spanning region. PROTAC: a small molecule that binds it is known.
Target class: Enzyme; Hydrolase
Gene: Protein-coding gene on chromosome 16 (14,672,548 to 14,694,308, reverse strand). Ensembl gene ENSG00000069764.
Subcellular location: Secreted; Lysosome; Cytoplasmic vesicle, secretory vesicle, acrosome
Pathways (Reactome):
Metabolism: Acyl chain remodelling of PC; Acyl chain remodelling of PE; Acyl chain remodelling of PG; Acyl chain remodelling of PI; Acyl chain remodelling of PS; Synthesis of PA
Gene Ontology:
Molecular function: 1-alkyl-2-acetylglycerophosphocholine esterase activity; phospholipase A2 activity; protein binding; calcium ion binding; phospholipase activity; phospholipid binding
Biological process: axon guidance; defense response to virus; low-density lipoprotein particle remodeling; lysophospholipid transport; negative regulation of transcription by RNA polymerase II; nuclear receptor-mediated signaling pathway; phosphatidic acid metabolic process; phosphatidylcholine catabolic process; phosphatidylcholine metabolic process; phosphatidylethanolamine metabolic process; phosphatidylglycerol metabolic process; phosphatidylserine metabolic process; platelet activating factor catabolic process; positive regulation of lipid storage; positive regulation of prostaglandin secretion; positive regulation of protein metabolic process; regulation of macrophage activation; signal transduction involved in regulation of gene expression; arachidonate metabolic process; cholesterol homeostasis; negative regulation of cholesterol efflux; positive regulation of acrosome reaction; positive regulation of arachidonate secretion; positive regulation of macrophage derived foam cell differentiation; arachidonate secretion; and 5 more
Cellular component: extracellular region; acrosomal vesicle; lysosome
Genetic constraint (gnomAD): Loss-of-function variants: 8 observed, 6.13 expected, observed/expected ratio (o/e) 1.3, 90% interval 0.74 to 1.89. That is too few expected variants to judge how well the gene tolerates losing a copy. Missense variants: 53 observed, 56.72 expected, observed/expected ratio (o/e) 0.93, 90% interval 0.75 to 1.17. Synonymous variants: 19 observed, 24.78 expected, observed/expected ratio (o/e) 0.77, 90% interval 0.53 to 1.12.
Homologues: Orthologues: chimpanzee PLA2G10 (99% identical), chimpanzee PLA2G10 (98% identical), macaque PLA2G10 (93% identical), pig PLA2G10 (72% identical), dog PLA2G10 (68% identical), mouse Pla2g10 (65% identical), guinea pig PLA2G10 (62% identical), rat Pla2g10 (62% identical), zebrafish pla2g10 (40% identical). Paralogues in human: PLA2G2D (34% identical), PLA2G2E (32% identical), PLA2G5 (31% identical), PLA2G2A (30% identical), PLA2G2F (30% identical), PLA2G1B (28% identical), OC90 (26% identical), PLA2G2C (24% identical).
Diseases named in the same sentence as PLA2G10 in open-access papers:
PLA2G10 is named in the same sentence as 30 diseases in open-access papers, as found by Europe PMC text mining. Sharing a sentence is not in itself a finding about the gene and the disease. The quoted sentences say what the papers report.
asthma (8 papers, 2010 to 2026). "Secreted phospholipase A2 group X (sPLA2-X) is implicated in human asthma and modulates airway hyperresponsiveness (AHR) and inflammation in murine models of allergic asthma." (PMID 41817596, 2026).
alopecia (3 papers, 2011 to 2023). Hair loss usually from the scalp. "Mice transgenically overexpressing human sPLA2-IIA (PLA2G2A-TG) or sPLA2-X (PLA2G10-TG) show striking skin abnormalities characterized by epidermal thickening, sebaceous gland hyperplasia, and alopecia, independently of inflammation." (PMID 37189415, 2023). "As in the case of transgenic mice overexpressing sPLA2-IIF, those overexpressing human sPLA2-IIA or sPLA2-X (PLA2G2A-TG and PLA2G10-TG, respectively) also develop alopecia and epidermal hyperplasia, accompanied by cyst formation, sebaceous gland hyperplasia, and a disturbed hair stem cell fate." (PMID 30546811, 2018). "Although systemic Pla2g10-Tg mice did not have any alveolar injury, we found a remarkable phenotype in these mice before weaning: they developed alopecia." (PMID 21673902, 2011).
atherosclerosis (3 papers, 2011 to 2022). A disease characterized by the build-up of fatty material and calcium deposition in the arterial wall resulting in partial or complete occlusion of the arterial lumen. "These in vitro observations may be relevant to cardiovascular pathology, since Pla2g10−/− mice are protected from angiotensin-II-induced aortic aneurysm and atherosclerosis." (PMID 21673902, 2011).
lung fibrosis (2 papers, 2023 to 2025). "Previous studies have shown that Pla2g10 expression increases in ciliated cells and KRT5−/KRT17+ cells but decreases in AT2 cells in a bleomycin-induced pulmonary fibrosis mouse model, with symptoms improving after intervention." (PMID 40278587, 2025). "Interestingly, all these six dominant isoforms were found to be present only in structural cells like fibroblasts (PLA2G2A and PLA2G5), mesothelial cells (PLA2G2A) and epithelial cells (PLA2G1B, PLA2G3, PLA2G10 and PLA2G12A) that are key players in lung fibrosis." (PMID 37048117, 2023).
Obesity (2 papers, 2016 to 2025). Accumulation of substantial excess body fat. "The sPLA2-X-dependent suppression of LXR can also occur in the adipose tissue, where Pla2g10 deficiency facilitates adipogenesis and obesity, and in the adrenal glands, where its deficiency promotes corticosteroidogenesis through the activation of steroidogenic acute regulatory protein." (PMID 29259680, 2016).
breast carcinoma (1 paper, 2021). "PLA2G10 is known as a novel modulator of lipid metabolism that promotes breast cancer cell growth and survival by stimulating LD formation and FA oxidation." (PMID 34768960, 2021).
colon cancer (1 paper, 2008). "The absence of tumour-related alterations in the gene expression of PLA2G2A and PLA2G10 in human sporadic colon cancer tissues is consistent with earlier studies." (PMID 18212756, 2008).
Down syndrome (1 paper, 2020). "Furthermore, this leads us to think about what PLA2G2A expression and PLA2G10 expression would be like if we were to compare Down syndrome patients with a non–Down syndrome control group." (PMID 32764374, 2020).
melanoma (1 paper, 2020). A malignant, usually aggressive tumor composed of atypical, neoplastic melanocytes. "Several PLA2 isoforms, i.e., pla2g6, pla2g7 and pla2g10, appeared to be upregulated in zebrafish V12RAS-driven melanoma, and PLA2G6 gene was associated with melanoma risk in humans." (PMID 33121001, 2020).
non-small cell lung carcinoma (1 paper, 2022). A group of at least three distinct histological types of lung cancer, including non-small cell squamous cell carcinoma, adenocarcinoma, and large cell carcinoma. "Phospholipase A2 Group X (PLA2G10) a member of the Phospholipase A2 family that encodes Phospholipase A2 as a predictive marker for non-small cell lung cancer, where alternative splicing leads to multiple transcriptional variants." (PMID 36713456, 2022).
cancer (7 papers, 2007 to 2025). A tumor composed of atypical neoplastic, often pleomorphic cells that invade other tissues. "PLA2G10 upregulation is widespread in human cancers and is associated with impaired T cell infiltration into tumor tissues." (PMID 39596471, 2024). "Carboxamines, such as N-Benzyl-4,6-difluoro-1H-indole-2-carboxamide, act as selective PLA2G10 inhibitors, and some related compounds have been proven to demonstrate anti-cancer activity, especially in pediatric brain cancer cell lines." (PMID 39596471, 2024). "The role of PLA2G10 in cancer progression has been reported previously." (PMID 35847988, 2022). "The network with the highest significance also contained several cancer-related genes with high expression levels, including DSG2, PRKCA, PLA2G10, and Grp94." (PMID 17726464, 2007).
tumor (5 papers, 2008 to 2025). "Moreover, PLA2G10 is overexpressed in M2-like tumor-associated macrophages (TAMs) in the TME in B cell lymphoma." (PMID 39596471, 2024). "Compared to adjacent normal tissues, tumor tissues exhibited significantly reduced expression of PTGIS, DGKB, HSD17B13, INMT, and ACACB, while PLA2G10, GRHL1, LIPG, and PLA2G4F were markedly upregulated." (PMID 40426878, 2025). "Reduces tumor weight, increases the levels of IFN-γ, TNF-α, GZMB and the expression of CLCA3, TFF3, AGR2, Zg16, Pla2g10, Guca2a." (PMID 35548468, 2022). "No variation in expression between the tumours and normal mucosa was observed for PLA2G1B, PLA2G2A, PLA2G2F, PLA2G10, PLA2G12A and PLA2G12B and for the M-type sPLA2 receptor (PLA2R1)." (PMID 18212756, 2008).
infection (2 papers, 2018 to 2024). The state of being infected such as from the introduction of a foreign agent such as serum, vaccine, antigenic substance or organism. "Two additional sPLA2 enzymes, PLA2G2D and PLA2G10, are also upregulated in the lungs of mice infected with influenza virus and are implicated in exacerbating infection outcomes." (PMID 39596471, 2024).
bacterial infection (1 paper, 2020). "On the other hand, VCAM1, PLA2G2A and PLA2G10, down-regulated genes, maintain, amongst other functions, close relationships with the defensive host response in the face of bacterial infection, inflammation and immune response regulation/suppression situations." (PMID 32764374, 2020).
PLA2G10 also shares sentences with these, for which no sentence is quoted: colitis (2 papers); lymphoma (2); adenocarcinoma (1); airway hyperresponsiveness (1); allergic asthma (1); B-cell lymphoma (1); chronic gastritis (1); colorectal cancer (1); cyst (1); diabetes (1); endometrial adenocarcinoma (1); leiomyosarcoma (1); metabolic disease (1); periodontal disease (1); respiratory failure (1); thyroid cancer (1).